ENSG00000251775
Gene: Small nucleolar RNA gene on chromosome 2 (63,883,249 to 63,883,391, reverse strand). Ensembl gene ENSG00000251775.
Homologues: Paralogues in human: SNORA59A (52% identical).